NLRP3 (NLR family pyrin domain containing 3)
Diseases named in the same sentence as NLRP3 in open-access papers (continued):
Sharing a sentence is not in itself a finding about the gene and the disease.
cystitis (continued). "Our central hypothesis was that NLRP3 inflammasome activity plays a protective role in MRSA acute cystitis." (PMID 38392844, 2024). "This study demonstrated that miR‐9‐enreched MSCs derived exosomes alleviate neuroinflammaiton and cystitis‐induced bladder pain by inhibiting TLR4/NF‐κb/NLRP3 signal pathway in interstitial cystitis mice, which is a promising strategy against cystitis‐induced bladder pain." (PMID 38415918, 2024). "We hypothesized that NLRP3 inflammasome activity plays a protective role in MRSA acute cystitis." (PMID 38392844, 2024). "Finally, we proved that EVs derived from miR‐9‐modified mesenchymal stem cells could alleviate neuroinflammation and cystitis‐induced bladder pain by inhibiting TLR4/NLRP3 pathway in interstitial cystitis mice." (PMID 38415918, 2024). "CYP-associated cystitis is likely a result of a complex crosstalk with a number of contributing factors that can include ROS production, oxidative stress, and TLR4 signaling, which in turn can increase the expression of inflammasome components, in particular the NLRP3 inflammasome." (PMID 38271096, 2024). "NF-κB family genes were also regulated during bladder infection in Nlrp3−/− mice and Nfkb expression was suppressed by SR140333 treatment of infected mice, supporting previous studies indicating that NF-κB might be involved as an upstream regulator of SP/NK1R and pro-inflammatory signaling." (PMID 30030504, 2018). "KZMK significantly inhibited the expression of NLRP3, GSDMD, and Caspase-1 in LPS-induced cystitis, further confirming its anti-inflammatory effects." (PMID 40004227, 2025). "In our previous research, we have proved that the TLR4/p65/NLRP3 signal pathway was been excessively activated, and played a key role in the spinal neuroinflammation in CYP-induced cystitis rats." (PMID 38020203, 2023). "In order to study the mechanism of LUT improving CYP-induced cystitis, we used western blot to study the expression changes of TXNIP/NLRP3 before and after LUT treatment." (PMID 34804174, 2021). "The results suggest that Asc and Nlrp3 regulate important aspects of NK1R and SP expression in acute cystitis." (PMID 30030504, 2018). "Our results suggest that injecting hUMSCs overexpressing HO-1 intrathecally can significantly promote functional outcomes in cystitis rats by reducing neuroinflammation, at least, partly through downregulating TLR4/p65/NLRP3 signaling pathway in the SDH region." (PMID 38020203, 2023). "Collectively, these results suggest that intrathecal injection of hUMSCs overexpressing HO-1 can significantly promote functional outcomes in cystitis rats by reducing neuroinflammation, at least, partly through downregulating TLR4/p65/NLRP3 pathway in the SDH region of CYP-induced cystitis rats." (PMID 38020203, 2023). "In the experimental UTI model, the most severe form of acute cystitis occurs in mice, lacking Asc or Nlrp3, which are inflammasome constituents." (PMID 34467240, 2021). "The most severe form of acute cystitis was detected in mice lacking the inflammasome constituents ASC or NLRP-3." (PMID 27732661, 2016). "Furthermore, specific depletion of NLRP3 in macrophages alleviated the severity of cystitis in diabetic mice, but not in non-diabetic mice." (PMID 36405726, 2022). "Severe, progressive cystitis in mice lacking ASC or NLRP-3, resembling chronic human disease." (PMID 27732661, 2016). "However, it is not known whether NLRP3 activation in macrophages during cystitis may differ in normal or diabetic setting as well as the importance of it." (PMID 36405726, 2022).
dementia (17 papers, 2018 to 2026). Loss of intellectual abilities interfering with an individual's social and occupational functions. "CCH-induced production of IL-1β, which is mediated by the NLRP3 inflammasome activation in the hippocampus, is a key pathological mechanism underlying dementia." (PMID 31766248, 2019). "This condition is linked with dementia onset because the production of inflammatory cytokines, like IL-1β, reduces Aβ phagocytosis, induces NLRP3-inflammasome activation with consequent release of NLRP3-related cytokines such as caspase-1 and IL-18, thus increasing amyloid-beta deposits." (PMID 30205543, 2018). "Supplementation with probiotics therefore has the potential to prevent the disease and delay dementia, as it can modulate the gut-brain axis by reducing NLRP3, TLR4 and MYD88 inflammatory pathways triggered by the overgrowth of pathogenic bacteria." (PMID 40376196, 2025). "It is widely acknowledged that NLRP3 inflammasome activation contributes to DM and dementia by triggering IL-1β maturation." (PMID 32425784, 2020). "Studies have shown that NLRP3, pro-apoptotic Bcl-2-related X protein (BAX), and anti-apoptotic protein B-cell lymphoma-2 gene (Bcl-2) are closely associated with the development of dementia." (PMID 41255822, 2025). "NLRP3, an inflammasome receptor, generates a chronic inflammatory environment and regulate the maturation of its downstream target Caspase-1, followed by apoptosis and cytokine release, leading to the development and progression of dementia." (PMID 38284892, 2024). "Therefore, targeted treatments on cholinergic system and NLRP3-related neuroinflammation may be beneficial for dementia symptoms." (PMID 38284892, 2024). "However, whether Evodia lepta could inhibit NLRP3 inflammasome in dementia was still unknown." (PMID 38284892, 2024). "No NLRP3 inhibitor has yet been successfully applied for dementia treatment." (PMID 39764140, 2024).
dilated cardiomyopathy (17 papers, 2014 to 2025). Cardiomyopathy which is characterized by dilation and contractile dysfunction of the left and right ventricles. "Elevated levels of NLRP3 inflammasomes, caspase-1, and IL-1β are observed in the peripheral blood of patients with dilated cardiomyopathy, with NLRP3 levels serving as an independent risk factor for readmission within 6 months." (PMID 39301029, 2024). "Doxorubicin-induced dilated cardiomyopathy was also associated with NLRP3 inflammasome-mediated pyroptosis." (PMID 35461308, 2022). "A mouse model of doxorubicin-induced dilated cardiomyopathy showed similar results where knockout of the gene for NLRP3 inhibited pyroptosis and reduced the extent of doxorubicin-induced left ventricular dysfunction." (PMID 38886277, 2024). "A significant activation of NLRP3 in the myocardium and increased expression of caspase-1, IL-1β, and IL-18 in patients with end-stage HF due to dilated cardiomyopathy indicates the role of pyroptosis in HF." (PMID 38886277, 2024). "This process exacerbates myocardial dysfunction and dilated cardiomyopathy induced by doxorubicin through NLRP3 inflammasome activation and subsequent cardiomyocyte pyroptosis." (PMID 38791409, 2024). "NLRP3 inflammasome activation through caspase‐1 will trigger cardiomyocyte pyroptosis to induce dilated cardiomyopathy, which will be regarded as a proper therapeutic target of dilated cardiomyopathy." (PMID 37125240, 2023). "Activation of the NLRP3 inflammasome and pro-inflammatory pyroptosis contribute to Dox-induced dilated cardiomyopathy." (PMID 36684601, 2022). "In a model of dilated cardiomyopathy, NLRP3 ablation was related to a general reduction in proinflammatory cytokines maturation, reduced mononuclear infiltrate, maintained myocyte organization and structure, and preserved systolic performance." (PMID 24744784, 2014). "Nevertheless, to date, most data about NLRP3-inflammasome implication in heart disease and inflammation come from murine models of ischemic damage and dilated cardiomyopathy." (PMID 24744784, 2014). "Furthermore, ROS accumulation induced by mitochondrial fission can activate the NLRP3 inflammasome, leading to cardiomyocyte pyroptosis in dilated cardiomyopathy (DCM)." (PMID 40804395, 2025). "Preliminary data suggest that exercise may effectively inhibit NLRP3 inflammasome activation in dilated cardiomyopathy (unpublished data)." (PMID 38681198, 2024). "Consequently, it is meaningful to investigate whether exercise can exert inhibitory effects on NLRP3 inflammasome activation and subsequent pyroptotic cell death in dilated cardiomyopathy." (PMID 38681198, 2024). "In dilated cardiomyopathy, Drp1 induced constitutive expression of NOX1 and NOX4 while promoted NLRP3 inflammasome activation through mitochondrial fission." (PMID 35711428, 2022).
endometrial cancer (17 papers, 2020 to 2025). Primary or metastatic malignant neoplasm involving the endometrium (mucous membrane that lines the endometrial cavity). "NLRP3 also plays a significant role in regulating macrophage polarization, oxidative stress, and immune response against endometrial cancer (EMC)." (PMID 40718836, 2025). "Estrogen-related receptor alpha (ERRα), a central regulator of cellular energy metabolism linked to poor cancer prognosis, enhances glycolytic metabolism and targets the NLRP3/caspase-1/GSDMD pathway to regulate pyroptosis in endometrial cancer." (PMID 40718836, 2025). "Estrogen has also been shown to enhance NLRP3, pro-IL-1β, and IL-1β expression, thereby promoting endometrial cancer progression through increased NLRP3 activation." (PMID 40718836, 2025). "Conversely, independent in vivo study claimed opposite conclusions, assigning, through MCC950 employment, protective roles to NLRP3 inflammasome in the management of endometrial cancer." (PMID 37891577, 2023). "A study in 2019 found that E2 acts through ERβ, enhances the activation of NLRP3 inflammasome, and promotes the progression of endometrial cancer." (PMID 37965452, 2023). "In a study conducted with 31 patients, oestrogen increased the growth of endometrial cancer cells by upregulating NLRP3 expression via the oestrogen receptor (ERβ)." (PMID 35877745, 2022). "A recent study demonstrated that hydrogen inhibited the growth of endometrial cancer through the pyroptosis pathway mediated by ROS/NLRP3/caspase-1/GSDMD, indicating there is a close relationship between pyroptosis and EC." (PMID 35299842, 2022). "ER is also involved in endometrial cancer cell proliferation through the up-regulation of NLRP3 expression." (PMID 35745570, 2022). "Recently, the expression of NLRP3, its inflammasome components and ERβ was analyzed in endometrial cancer tissue samples from 31 patients." (PMID 34064909, 2021). "Molecular analysis showed that estrogens enhanced the proliferation of endometrial cancer cells by upregulating NLRP3 expression via ERβ." (PMID 34064909, 2021). "We observed LDH and IL-1β release to be increased in hydrogen-treated endometrial cancer cells that were upregulated by LPS and nigericin or downregulated by ROS, NLRP3, or the caspase-1 inhibitor." (PMID 31924176, 2020). "Collectively, these results indicate that upregulated NLRP3 expression promotes the progression of endometrial cancer." (PMID 33613533, 2020). "Our data demonstrated that GSDMD was recruited to the NLRP3 inflammasome after LPS and nigericin priming in endometrial cancer cells, and that GSDMD was required for mediation by the NLRP3 inflammasome of pyroptosis and IL-1β production." (PMID 31924176, 2020). "In the present study, we found that the NLRP3 inflammasome (including NLRP3 and caspase-1 expression) was upregulated in endometrial cancer tissue compared to that of benign tissues." (PMID 31924176, 2020). "In contrast, overexpression of NLRP3 enhances the activities of proliferation, migration and invasion as well as increasing caspase-1 activation and IL-1β secretion in human endometrial cancer cells." (PMID 33613533, 2020). "In summary, the NLRP3 inflammasome promotes endometrial cancer progression." (PMID 40718836, 2025). "Immunohistochemistry was used to assess the expression of four pyroptosis-associated molecules (NLRP3, cleaved caspase-1 p20, cleaved gasdermin D, and CHMP4B) in 351 patients with endometrial cancer, and their associations with clinical, pathological, and survival outcomes were analyzed." (PMID 38562170, 2024). "Many studies have been conducted to attribute the tumorigenesis of endometrial cancers to NLRP3." (PMID 35877745, 2022). "Therefore, the different roles of estrogen/ERβ/NLRP3 inflammasome activation may be related to estrogen levels and ERβ expression in endometrial cancer patients." (PMID 34064909, 2021).
endometrial cancer (continued). "This study extended our original analysis of the ability of hydrogen to stimulate NLRP3 inflammasome/GSDMD activation in pyroptosis and revealed possible mechanism (s) for improvement of anti-tumor effects in the clinical management of endometrial cancer." (PMID 31924176, 2020). "We observed overexpression of NLRP3, caspase-1, and GSDMD in human endometrial cancer and cell lines by IHC and western immunoblotting." (PMID 31924176, 2020). "Since the initial pyroptotic signals ROS and the NLRP3 inflammasome were potential targets of molecular hydrogen, and because increased tumor cell ROS could promote cancer cell death, we investigated whether treatment with hydrogen was able to boost ROS accumulation in endometrial cancer cells." (PMID 31924176, 2020). "We performed immunohistochemical staining and western immunoblotting analysis to observe expression of NLRP3, caspase-1, and GSDMD in human and xenograft mice endometrial cancer tissue and cell lines." (PMID 31924176, 2020). "The role of NLRP3 in promoting invasion has been demonstrated with human endometrial cancer cell lines such as Ishikawa and HEC-1A cells, where knockdown of NLRP3 significantly reduces proliferation, clonogenicity, invasion and migration." (PMID 33613533, 2020). "We observed over-expression of NLRP3, ASC, pro-caspase-1, caspase-1, and GSDMD in Ishikawa and HEC1A endometrial cancer cell lines in contrast to endometrial epithelial cells." (PMID 31924176, 2020). "Another study assessed the expression of four pyroptosis-related molecules (NLRP3, cleaved caspase-1 p20, cleaved gasdermin D, and CHMP4B) in 351 endometrial cancer patients via immunohistochemistry and analyzed their associations with clinical, pathological, and survival outcomes." (PMID 40718836, 2025). "Another study discussing a contrary result show that although NLRP3 is present in higher quantities in endometrial cancer cells, caspase-1 and IL-1β are not expressed in a correspondingly high fashion." (PMID 35877745, 2022). "Upregulated expression of NLRP3, caspase-1, and GSDMD were detected in endometrial cancer tissues (N = 546) compared with normal endometrium (N = 35) in TCGA database, significantly difference was seen in NLRP3 and GSDMD in sample type and histological types (P < 0.05)." (PMID 31924176, 2020). "Additionally, immunohistochemistry (IHC) and protein immunoblotting studies have shown overexpression of NLRP3, caspase-1, and GSDMD in human endometrial cancer tissues and cell lines, with moderate to strong positive staining for these proteins in tumor sections." (PMID 40718836, 2025). "Studies have reported that pyroptosis-related protein caspase-1, NLRP3 and GSDMD were highly expressed in endometrial cancer tissue, and hydrogen could inhibit the growth of endometrial cancer by inducing GSDMD-mediated pyroptosis through a ROS/NLRP3/caspase-1 pathway." (PMID 34381721, 2021). "Furthermore, our investigation revealed that high expression of NLRP3, the initiator of the canonical pyroptotic pathway responsible for activating caspase-1, was linked to adverse RFS, specifically in advanced endometrial cancer, although not across all stages of endometrial cancer." (PMID 38562170, 2024).
Glucose intolerance (17 papers, 2016 to 2024). Glucose intolerance (GI) can be defined as dysglycemia that comprises both prediabetes and diabetes. "We tested the hypothesis that loss of Nlrp3 would protect mice from Western diet-induced adipose tissue (AT) inflammation and associated glucose intolerance and cardiovascular complications." (PMID 27583382, 2016). "Depletion of macrophages, NLRP3 or IL-1β protected mice from air pollution-induced glucose intolerance." (PMID 37400850, 2023). "The changes in NLRP3 inflammasome activity are believed as a major contributor to glucose intolerance in BMT-APPL1 KO mice." (PMID 34789781, 2021). "Studies suggest that NLRP1 and NLRP3 activity levels alter metabolic homeostasis and can thereby contribute to glucose intolerance and insulin resistance." (PMID 29515457, 2018). "Although Western diet promoted glucose intolerance in both WT and Nlrp3-/- mice, Nlrp3-/- mice were protected from Western diet-induced aortic stiffening." (PMID 27583382, 2016). "In conclusion, findings from the present study indicate that Western diet-induced glucose intolerance and AT inflammation is Nlrp3-independent." (PMID 27583382, 2016). "We hypothesized that NLRP3 could be involved in air pollution-induced gut inflammation and glucose intolerance." (PMID 37400850, 2023). "Lastly, we assessed whether the involvement of NLRP3 in air pollution-induced glucose intolerance was mediated by the secretion of IL-1β as a potential target for a therapeutic intervention." (PMID 37400850, 2023). "The role of NLRP3 signaling was also confirmed in vivo as deletion of NLRP3 or anti-IL-1β treatment reversed the pro-inflammatory milieu in the gut, insulin secretion defect and glucose intolerance." (PMID 37400850, 2023). "Although Nlrp3 deficiency did not affect AT inflammation and/or glucose intolerance, we did observe that Nlrp3-/- mice were protected from a Western diet-induced increase in aortic stiffness." (PMID 27583382, 2016). "Furthermore, AT inflammation and glucose intolerance caused by Western diet were not attenuated in Nlrp3-/- mice." (PMID 27583382, 2016). "Conversely, genetic depletion of the NLRP3 inflammasome in mice prevented DEP-induced gut inflammation and glucose intolerance." (PMID 37400850, 2023). "Banxia Houpu decoction is believed to restore glucose intolerance in CUMS rats by improving insulin signaling and suppressing NLRP3 inflammasome activation in the liver and brain." (PMID 35957821, 2022). "Regarding the glycemic control upon DEP exposure, Nlrp3-/- mice did not develop glucose intolerance." (PMID 37400850, 2023). "Besides, BXHPD restored glucose intolerance in CUMS rats by improving insulin signalling and suppressing NLRP3 inflammasome activation in the liver and brain." (PMID 37581474, 2023). "Taken together, it is possible that our finding that ablation of Nlrp3 did not protect mice from glucose intolerance may be attributable to counteracting effects from the gut in a setting of standard co-housing facilities and/or reduced IL-18 signaling." (PMID 27583382, 2016).